CD4 (CD4 molecule)
Diseases named in the same sentence as CD4 in open-access papers (continued):
Sharing a sentence is not in itself a finding about the gene and the disease.
tumor (continued). "CD4+ Tcm was found to be significantly lower in tumor tissues, while CD4+ Tem, CD8+ naïve T cells, and CD8+ Tcm were significantly higher." (PMID 32728493, 2020). "Combining DT-mediated Treg cell depletion with αIL-2 had little impact on Ki67, T-bet, IFN-γ, and GM-CSF expression in CD4+ T cells in either LN or tumor." (PMID 31924474, 2020). "To investigate this possibility, we quantified the percentage of Tregs in CD4+ T cells in tumor specimens and co-cultured total tumor CD4+ T cells with peripheral blood monocytes." (PMID 32973804, 2020). "PDAC is considered an “immunologically cold” tumor because of the high infiltration of Tregs and MDSCs and the consequent impairment of CD4+ and CD8+ cell-mediated antitumor responses." (PMID 35582441, 2020). "Both absolute and relative number of lymphocytes (CD45highCD11b-) were decreased in the brains of tumor animals compared to sham animals starting at 5 d.p.i., which was driven by a decrease in B-cells and CD4+ T-cells." (PMID 32391790, 2020). "CD4+ T cells also play critical roles in regulating many aspects of adaptive immunity, and various subsets of CD4+ T cells exhibit both pro-tumor and anti-tumor activities." (PMID 32401825, 2020). "Although much attention has been paid to the role of CD8+ cytotoxic T cells in tumour protection, we provide convincing evidence that CD4+ helper T cells play a critical role in cancer immune responses in animal models and also in patients." (PMID 32708397, 2020). "Tumor control was correlated with increased tumor T-cell infiltration and was abrogated when CD4+ and CD8+ T-cells were depleted." (PMID 33614492, 2020). "The immune system works as a barrier to tumor formation and progression and several studies have shown that CD8+ cytotoxic T lymphocytes (CTLs), CD4+ Th1 T cells, and natural killer (NK) and dendritic cells (DC) are critical to block tumor development." (PMID 30959975, 2019). "It has also become clear that many tumor-derived molecules or extracellular vesicles likely influence the differentiation of CD4+ T cells." (PMID 31300052, 2019). "Most tumor-infiltrating CD4+ T cells expressed PD-1 in response to RTx and combination of RTx with HHP vaccine enhanced it further significantly." (PMID 31555582, 2019). "In the present study, 4/21 ICR-CAR T cells highly expressed RORγt and displayed Th17-like phenotypes in vitro and performed potent anti-tumor activities with persistence of CD4+ T cells in vivo." (PMID 31379876, 2019). "From our study, E.G7 tumor evasion of CD4+ T cell activation was primarily due to a secreted factor and not a cell contact-dependent mechanism that acted on the JAWS II DC." (PMID 31602007, 2019). "In previous studies, we reported that a subset of NY-ESO-1-specific CD4+ T cells directly recognizes NY-ESO-1-expressing cancer targets in a MHC class II-restricted manner (tumor-recognizing CD4+ T cells or TR-CD4 cells)." (PMID 30626427, 2019). "Consistent with previous results, the frequencies of IL-10+ and IL-21+ CD4+ T cells and IL-10+ B cells in tumor-draining lymph nodes and tumor tissues from Il6−/− tumor-bearing mice were significantly decreased." (PMID 31300052, 2019). "Lastly, CD4+ T cells can target tumor cells indirectly by modulating the tumor microenvironment or directly by cytolytic mechanisms 7-10." (PMID 31754392, 2019). "GM-CSF can stimulate and activate antigen-presenting cells (APCs), which can process and present tumor antigens to CD4+ helper T cells and CD8+ cytotoxic T lymphocytes (CTL)." (PMID 31338094, 2019). "T cells, especially CD4+ T cells, are an important part of the tumor immune inflammatory microenvironment." (PMID 31018021, 2019). "Our survey revealed that the combination of an antigen-specific protein vaccine with anti-PD-L1 therapy increased the number of tumor-infiltrating CD4+ and CD8+ T cells within tumors." (PMID 31546897, 2019).
tumor (continued). "The result showed that cryo-thermal-activated eosinophils have the capacity to directly activate the anti-tumour CD4+ T cells and cytotoxic CD8+ T cells." (PMID 31519961, 2019). "Below, we discuss the pathways throughwhich tumor-derived vesicles can affect CD4+/CD8+ T cells in more detail." (PMID 31993233, 2019). "Although the response of the T-cell lines to peptide-loaded autologous DCs appeared higher than tumor cell lines, unloaded DCs didn’t stimulate PD-L1241-265-specific CD4+ T-cells as much as tumor cell lines." (PMID 31221178, 2019). "Here, we use single-cell mRNA sequencing to analyze the response of tumor-specific CD4+ TILs and draining lymph node (dLN) T cells." (PMID 31801070, 2019). "We and others have reported that the presence of tumor-infiltrating CD4+ or CD8+ T cells and the ratio of tumor-infiltrating FOXP3+ Tregs to CD4+ T cells were favorable and unfavorable prognosticators, respectively, in patients with PDAC." (PMID 30800224, 2019). "This study revealed that the CD4+Foxp3+ Treg frequency is increased in both the peripheral blood and tumor biopsies from BC patients compared with healthy controls and is highest in BC tissues." (PMID 30718502, 2019). "IFN-γ secreting CD4+ T cells facilitate the differentiation of tumor antigen-specific CTLs and promote the recruitment of cells from the immune system participating in tumor cell containment." (PMID 31024545, 2019). "The TME of EGFR mutated NSCLC, as in other tumours, includes several cells of the immune system: tumour-associated macrophage (TAM), T cell CD4+, CD8+, regulatory T cell (Treg FOXP3+), and mast cells." (PMID 31554160, 2019). "Some of these tumor antigens recognized by CD4 T cells belong to the same categories as those recognized by cytotoxic CD8 T cells." (PMID 30953535, 2019). "The anti-tumor activity of B cells in the setting of MEK inhibitor plus PD1 inhibitor was more than the anti-tumor activity of CD4 T cells, but less than the activity of CD8 T cells." (PMID 31671149, 2019). "The complex role of CD4+ T-cells in anti-tumour immunity reveals various functions of several types of CD4+ T-cells." (PMID 31434983, 2019). "Mechanisms of expansion/proliferation or trafficking of these CD4+ T cell subsets into tumor sites warrants further investigations." (PMID 31921188, 2019). "As expected from the lack of reactivity to this cancer cell line in vitro, CD8SP-TCR-transduced CD4+ T cells showed negligible inhibition of tumor growth in vivo." (PMID 30626427, 2019). "Upon tumor antigen stimulation, activated memory CD4+ T cells respond very early to impede extensive replication or any significant impairment, either directly attacking the invading organism or providing assistance to B or cytotoxic T cells." (PMID 31080362, 2019). "Introtumoral administration of LDH@155 reduces the percentage of TAMs and MDSCs in the tumor and elevates CD4+ and CD8+ T cell infiltration and activation, which can promote therapeutic efficiency of α‐PD‐1 antibody immunotherapy." (PMID 31016114, 2019). "This is in part because high-affinity MHC class I-restricted TCR confers tumor-reactivity to CD4+ T cells in addition to CD8+ T cells by bypassing the requirement of CD8 co-ligation for activation." (PMID 30626427, 2019). "Using multicolor flow cytometry, we found that around 50% of CD45+ tumor infiltrating leukocytes were Cd11b+ myeloid cells, and CD4+ T cells were the most common T lymphocyte cell type in IgG-treated CCK168 control carcinomas." (PMID 30832732, 2019). "As the field of cancer immunology further evolves, several additional questions are raised: what is the role of CD4+ T-cells in vaccine-induced anti-tumor responses?" (PMID 30723469, 2019). "Our study unveils novel cellular and molecular mechanisms of tumor-derived extracellular vesicles in regulating CD4+ effector T cell function and pinpoint TRAPs as a therapeutic target for cancer immunotherapy." (PMID 31300052, 2019).
tumor (continued). "Nonetheless, CD4+ T cells have been recently found to exert a broad range of action in tumor rejection." (PMID 31812953, 2019). "In the context of adoptive T-cell transfer, the capacity of tumor-reactive CD4+ and CD8+ T cells to infiltrate tumors requires the local production of C3, complement activation and release of C5a." (PMID 31031765, 2019). "To assess the impact of TIL-Bs on survival and functional capacity of T cells, we cultivated Bhi tumor-derived cell suspensions and analyzed the viability and cytokine production of CD4+ and CD8+ T cells after B cell depletion (n = 4)." (PMID 31623665, 2019). "Most of CD4+ T cells were depleted in the tumor and draining lymph nodes after mice were treated with αCD4." (PMID 30696484, 2019). "Accordingly, CD4− iNKT cells mount direct cytotoxicity against tumor target cells which can be mediated via TCR-CD1d interactions or directly via NKG2D engagement." (PMID 31569599, 2019). "Second, Tα1 fused with the Fc domain of human IgG4 plays anti-tumor effects in the 4T1 and B16.F10 tumor xenograft models by upregulating CD86 expression, secreting IFNγ and IL-2, and increasing the number of tumor-infiltrating CD4+ and CD8+ T cells." (PMID 31555601, 2019). "CAELYX® alone also increased the number of CD3+ T cells in the tumor compared to controls, while lowering the number of CD4+ T cells in the tumor microenvironment compared to controls, monotherapies, and the combination therapy." (PMID 30670061, 2019). "Until now, we focused on CD8+ cytotoxic T cells, but CD4+ T helper cells also have an important contribution in shaping anti-tumour immune responses." (PMID 30232514, 2019). "The arginine increment elicited by Cpd9 was associated with an increase in tumor T cells, the levels of CD3, CD4 and CD8 cells increased in the tumor microenvironment (CD3 p < 0.01, CD4 p < 0.007 and CD8 p < 0.07)." (PMID 30728077, 2019). "Tumor-infiltrating CD4+ Tregs were frequently detected in the TME and suppress CTL activity leading to reduced anti-tumor T cell responses." (PMID 31555274, 2019). "CD4+ T cells play a critical role in modulating both innate and adaptive anti-tumor immune responses." (PMID 31300052, 2019). "DCs involved in the initiation of the anti-tumor T cell response also benefit from CD4+ T cell help, as CD40/CD40L interaction with CD4+ T cells is required to fully activate DCs that can subsequently generate CD8+ TEFF and long-lasting CD8+ T cell memory." (PMID 31379821, 2019). "The depletion of Tregs characterized by CD4+, CD25hi was assessed in the periphery of vaccinated mice on day 6 post tumor transplantation." (PMID 31156619, 2019). "Autopsy of the metastatic lesions revealed that infiltrating CD4+ T cells in tumor tissue were enriched for AMBI-1 clones." (PMID 31616431, 2019). "A recent study reported that CD26HiCD4+ T cells exhibit superior anti-tumor activity to CD26int/− CD4+ T cells." (PMID 31783783, 2019). "Overall, these data demonstrated that CAH‐mediated PDT potentiated local and systemic anti‐tumor immunity by activation of CD4+CD8+ double T cells accompanied with increased proinflammatory cytokines production." (PMID 30886812, 2019). "Our previous studies performed in mice bearing EL4-huCD20 tumor cells have demonstrated that a protective CD4+ T cell response directed against human CD20 molecule is induced after mAb treatment." (PMID 31494742, 2019). "Increases IFN-γ and higher numbers of tumor-infiltrating CD4+ lymphocytes.The generation of IL-6, IL-12, IL-23 and TNF-α in dendritic cells increases rapidly." (PMID 31083446, 2019). "Representative peak plots (middle) and statistical histograms (below) showing the percentage of PD-1+CD4+ T cells in the tumor microenvironment." (PMID 31511064, 2019). "Detailed assessment of the tumor microenvironment from treated mice identified increased numbers of infiltrating CD4+ and CD8+ T cells in both treatment arms, but at higher levels upon chemo-immunotherapy." (PMID 30630527, 2019).
tumor (continued). "Intratumoral Tregs express CD4 and FoxP3 in both human and mouse and play a suppressive role in anti-tumor immunity." (PMID 31771616, 2019). "In a lung adenocarcinoma mouse model engineered to express MHC class II-restricted cytosolic antigen, activated cDC2 are observed both in the tumor and dLN and antigen-specific naïve CD4 T are activated in the dLN." (PMID 31143179, 2019). "On the other hand, a large number of studies have shown that EMT tumor cells can induce enhanced tumor infiltration of deviated immune cells, such as polymorphonuclear MDSCs, myeloid cells, mast cells, or natural CD4+CD25− Tregs." (PMID 31096701, 2019). "In the mice bearing knock-down B16F10 tumors, the frequency of IL-21+ and IL-10+ CD4+ T cells in the tumor draining lymph node and tumor tissue and the serum IL-6 level were significantly reduced as compared to those in the mice bearing control tumors." (PMID 31300052, 2019). "CD4+ T cells also exert direct anti-tumor and anti-viral roles based on their cytolytic activity and effector cytokine secretion." (PMID 31156634, 2019). "Memory recall capability was shown by adoptive cell therapy and while transferred CD8+ T cells were poor in controlling tumor growth, transfer of memory CD4+ T cells was capable of resolving established tumors, albeit when injected in high numbers." (PMID 31379821, 2019). "Transient depletion of CD4+ immunosuppressive cells in the tumor-bearing host represents another potential anti-tumor therapeutic strategy against cancer." (PMID 30696484, 2019). "Flow cytometry confirmed the tumor-specific presence of activated (CD4+PD-1++CD161−CD38+HLA-DR+ and CD8+CD103+CD161−NKG2A+/−PD1++CD38++HLA-DR+) effector memory T cells." (PMID 31481117, 2019). "In C57BL/6J mice, the percentages of CD3+ T and CD56+ NK cells were decreased, but the ratio of CD4+ Th/CD8+ Tc elevated after tumor inoculation." (PMID 31781219, 2019). "Lymphocytes within the tumor expressed CD4, CD8, TdT and CD1a, a pattern consistent with thymocytes." (PMID 31639039, 2019). "Control-treated CCK168 and CCK169 tumors, had a significantly greater CD4+ T cell content than tumors of the unresponsive tumor lines (p = 0.001)." (PMID 30832732, 2019). "On the other hand, suppressive Foxp3+ regulatory T (Treg) cells, which represent a significant proportion of the CD4+ population in tumors, have been shown to increase with tumor stage and correlate with poor prognosis in invasive carcinomas." (PMID 31555258, 2019). "Tumor-specific CD4+ T cells in the tumor microenvironment can be reprogrammed into regulatory CD4+ T cells (Tregs) that counteract cytotoxic T cell activity and are generally considered to contribute to an immuno-suppressive tumor microenvironment." (PMID 31754392, 2019). "Tumor cell-derived EVs induced the conversion of human conventional CD4+CD25– T cells to CD4+CD25hiFOXP3+ Treg cells in a TGF-β1–dependent manner." (PMID 31680949, 2019). "Sustained anti-tumor CD4+ T cell “memory-like” formation was also shown in a vaccine trial of prostate cancer patients utilizing the AE37 vaccine and the DR11/AE37 tetramer to identify AE37 specific T cells." (PMID 31379821, 2019). "In conclusion, TRAPs-educated CD4+ T cells play an important role in promoting tumor growth by inhibiting effector T cell function." (PMID 31300052, 2019). "With increases in tumour grade, the proportions of both CD8+ and CD4+ tumour-infiltrating T cells improve." (PMID 31729963, 2019). "We further demonstrated that the level of S1P1 was increased in tumor tissues from BC patients with a higher frequency of tumor-infiltrating CD4+Foxp3+ Tregs than in those from BC patients with a lower frequency of tumor-infiltrating CD4+Foxp3+ Tregs (n = 3)." (PMID 30718502, 2019). "Despite evidence for clinical potential of CD4+ tumor-infiltrating lymphocytes (TILs), their functional diversity limits our ability to harness their activity." (PMID 31801070, 2019).
tumor (continued). "Upregulation of IRF7 in treated cancer cells promoted resistance to chemotherapy, reduced cell growth and induced switching of the response from a myeloid derived suppressor cell-dominated immune response to a CD4+/CD8+ T cell-dependent anti-tumor response." (PMID 30546090, 2019). "High levels of tumor infiltrating lymphocytes (CD4+ and CD8+) should be considered, in NSCLC, as an independent positive prognostic factor for OS and for higher RR to ICI treatment." (PMID 31590386, 2019). "TH1 CD4+ T cell responses can support anti-tumor immunity, in part due to the direct impact IFN-γ has on tumor cells." (PMID 31379821, 2019). "As importantly, they underscore the importance of tumor-reactive CD4+ T cells in mediating anti-tumor immunity." (PMID 31362778, 2019). "Once injected, dendritic cells (DCs) play a crucial role by taking up the vaccine and presenting the vaccine-derived tumor epitope in the context of major histocompatibility class (MHC) I or II complexes to CD8+ or CD4+ T cells, respectively." (PMID 31040852, 2019). "Another study showed that anti-CD20 mAb engages FcγRIIA expressed on dendritic cells leading to the priming of self-reactive tumor-specific CD4+ T cells." (PMID 31494742, 2019). "We sought, therefore, to study the predictive values of memory CD8+ T, memory CD4+ T, naïve CD8+ T, and naïve CD4+ T for tumor response to SBRT in patients with NSCLC lung metastases." (PMID 31080362, 2019). "CD4 T-cell responses that are specific for neoantigens exert their helper function at the level of the DC and enhance the activation of anti-tumor CD8 T cells." (PMID 31221199, 2019). "FIP200 deletion induced an anti-tumor immune response mediated by CD8+ and CD4+ T cell infiltration to the tumor site, mediated by IFNγ and chemokine secretion (CXCL9, CXCL10, CXCL11) by autophagy-deficient tumor cells." (PMID 31554173, 2019). "Further analysis confirmed the positive correlation between the numbers of Fas+CD4+ T cells and IL-9+CD4+ T cells in the tumor tissues." (PMID 31266950, 2019). "We suggest that a comprehensive analysis of CD4+CD8+ double-positive T-cell clones in the periphery or tumor tissues would yield important insights into T-cell ontogeny and function." (PMID 30626427, 2019). "Kwak and colleagues also observed enhanced IL-10 expression in CD4+ and CD8+ T lymphocytes in lungs of tumor-bearing C3-deficient mice." (PMID 31379815, 2019). "Further studies are necessary to confirm the correlation between clinical efficacy of PD-1/PD-L1 antibodies and the density of CD4+ T cells and Foxp3+ Treg cells in the tumor microenvironment." (PMID 30978241, 2019). "Profiling of CD4 T‐cell subsets can help identifying patients with a high probability of responding to immunotherapy, especially in combination with PD‐L1 tumor expression." (PMID 31273938, 2019). "Consistently, in B16F10 tumor-bearing mice, the frequency of IL-6+, IL-21+ and IL-10+ CD4+ T cells in the draining lymph node and spleen were also increased." (PMID 31300052, 2019). "First, we compared the capacity of isolated tumor-infiltrating ST2+ versus ST2− CD4+ FOXP3+ Tregs to suppress CD4+ responder T cells from naive St2−/− donor mice in vitro." (PMID 31165767, 2019). "The fraction of T cells CD4 memory resting was significantly different among four tumor stages of cancer (P = 0.027)." (PMID 31681739, 2019). "Nevertheless, the primed and boosted CD4+ T cells produced high amounts of the anti-tumor-cytokine IFNγ indicating that in spite of the presence of potentially immunosuppressive T cell subsets effective anti-tumor-activity is generated." (PMID 30956760, 2019). "Peritumorally-injected BMCs remained within the tumor for at least 14 days and tritherapy efficacy was dependent on both CD4+ and CD8+ T cells." (PMID 31747946, 2019).